IL21 (interleukin 21)
Diseases named in the same sentence as IL21 in open-access papers (continued):
Sharing a sentence is not in itself a finding about the gene and the disease.
lymphedema (2 papers, 2009 to 2024). Excess fluid collection in tissues, causing swelling. "To address the role of Th17 cells in filarial lymphedema, we examined the expression of IL-17A, IL-17F, IL-21 and IL-22 as well as the upstream inducing cytokines IL-23, IL-6 and IL-1β in PBMCs of lymphedema patients following BmA or PPD stimulation." (PMID 19381284, 2009). "In our study, we found augmented induction of IL-17A, IL-17F, IL-21, and IL-23 in patients with filaria-induced lymphedema." (PMID 19381284, 2009). "Babu and collaborators demonstrated that the expression of the Th17 cytokines IL-17A, IL-17F, IL-21, and IL-23 was significantly upregulated in filaria-infected patients with lymphedema, suggesting a role for Th17 cells in the pathogenesis of filaria-induced pathology." (PMID 38587077, 2024). "Notably, expression of the Th17 family of cytokines—IL-17A, IL-17F, IL-21, and IL-23—was also significantly upregulated by BmA stimulation in lymphedema patients." (PMID 19381284, 2009). "Most effector cytokines known to be produced by Th17 cells—IL-17A, IL-17F, and IL-21 (with the exception of IL-22)—are induced at significantly higher levels in patients with lymphedema, suggesting an important role for these cytokines in development of this disease process." (PMID 19381284, 2009).
myeloid malignancies (2 papers, 2022 to 2023). "In this phase I/II clinical trial, we investigated the safety and efficacy of high doses of mb-IL21 ex vivo expanded donor-derived NK cells to decrease relapse in 25 patients with myeloid malignancies receiving haploidentical stem-cell transplantation (HSCT)." (PMID 34312462, 2022). "In the phase I/II trial, high doses of membrane-bound IL-21 (mb-IL21) ex vivo expanded donor-derived NK cells (NCT01904136) resulted in lower 2-year relapse rate with better disease-free survival (DFS) in patients suffering from various myeloid malignancies." (PMID 37228595, 2023).
nasopharyngeal carcinoma (2 papers, 2022 to 2024). A carcinoma arising from the nasopharyngeal epithelium. "Further studies are required to explore whether IL-21 or other germinal center cytokines might likewise de-repress or boost LMP1 expression in EBV+ epithelial cell tumors, including gastric and nasopharyngeal carcinoma." (PMID 38683861, 2024).
ovarian tumor (2 papers, 2014 to 2021). "For the first time, the expression of genes encoding IL-21 and IL-22 was assessed at the mRNA level in ovarian tumor specimens." (PMID 34300224, 2021). "The aim of the analysis was for the first time to assess the expression of genes encoding IL-21 and IL-22 at the mRNA level in ovarian tumor specimens and the concentration of these parameters in serum and peritoneal fluid in patients with ovarian serous cancer." (PMID 34300224, 2021).
pancreatitis (2 papers, 2014 to 2025). Inflammation of the pancreas. "Although research on IL-21 and pancreatitis is relatively limited, studies have begun to explore the potential connection between IL-21 and PC." (PMID 39958351, 2025). "The IL-21 dose was reduced in 3 patients due to myalgias, pancreatitis, and rash, respectively." (PMID 24829759, 2014).
periapical granuloma (2 papers, 2016). Chronic nonsuppurative inflammation of periapical tissue resulting from irritation following pulp disease or endodontic treatment. "On estimation of IL-21 levels in periapical granulomas, it was demonstrated that IL-21 along with IL-17A, TNF-α (tumour necrosis factor-α), and IFN-γ were higher in active periapical granulomas, while IL-4, IL-9, IL-10, and IL-22 were higher in inactive periapical granulomas." (PMID 26998377, 2016). "Since B cells are predominant in chronic lesions like periapical granulomas, it would be possible to speculate that IL-21 contributes to a Tfh-B cell response axis in periapical areas, similar to that of tertiary lymphoid tissues associated with chronic infection sites." (PMID 26998377, 2016).
polymyositis (2 papers, 2025). A rare idiopathic inflammatory myopathy characterized by symmetric proximal muscle weakness and elevated muscle enzymes. "The deletion of a 39 kb DNA fragment located 10 kb upstream of the interleukin IL21/IL2 locus is associated with the development of polymyositis." (PMID 40520426, 2025). "Our study unequivocally demonstrates the involvement of the IL21/IL2 locus in polymyositis in the Kooiker dog." (PMID 39746095, 2025). "We suggest that elements located 10–49 kb upstream of the IL21/IL2 locus play an important role in the regulation of the canine genes and that deletion of these elements is a risk factor for polymyositis in Kooiker dogs." (PMID 39746095, 2025). "The overexpression of IL21 in affected dogs is associated with activating the JAK1 and JAK3 receptors, suggesting that targeting this signalling cascade with JAK inhibitors may provide a novel therapeutic approach for polymyositis in the Dutch Kooiker dog." (PMID 40520426, 2025).
primary immunodeficiencies (2 papers, 2014 to 2016). "Patients with primary immunodeficiency caused byIL21R orIL21 mutations have been described, and their phenotypes have provided invaluable insights into the role of IL-21 in host defense." (PMID 26966515, 2016). "Moreover, reports describing patients with primary immunodeficiency caused byIL21 orIL21R mutations underscore the critical role of IL-21 in host defensein vivo in humans." (PMID 26966515, 2016). "We will also focus on the role of IL-21 and defects in B-cell function and how these contribute to human immunopathologies such as primary immunodeficiencies and B-cell mediated autoimmune conditions." (PMID 24600453, 2014).
prostate carcinoma (2 papers, 2010 to 2025). A carcinoma that arises from epithelial cells of the prostate gland. "IL-21 is involved in T-helper type 17 (Th17) effector cell function, which has been implicated in prostate cancer development and more recently with progression to metastasis." (PMID 20184734, 2010). "No studies have to date investigated the potential role of IL21 variation in prostate cancer susceptibility." (PMID 20184734, 2010). "Similarly to IL-2, IL-21 is expressed by activated CD4+ T-cells and has been described as having anti-tumor effects in mouse models for several different malignancies, including prostate cancer." (PMID 20184734, 2010).
pulmonary arterial hypertension (2 papers, 2022 to 2023). Pulmonary arterial hypertension (PAH) is a group of diseases characterized by mean pulmonary artery pressure >20 mmHg and elevated pulmonary arterial resistance leading to right heart failure. "In pulmonary arterial hypertension, IL-21 promoted the polarization of primary alveolar macrophages toward the M2 phenotype." (PMID 37628738, 2023). "IL-21 promotes the primary alveolar macrophages toward the M2 phenotype polarization in pulmonary arterial hypertension (PAH)." (PMID 35954166, 2022).
Renal failure (2 papers, 2018 to 2020). "Renal failure was significantly associated with elevation of IL-21 and IL-23, while patients with liver involvement had a significant elevation of IL-21, IL-23, and TNF-α." (PMID 30123395, 2018). "When the cytokine levels of patients with mild disease and renal failure were compared, IL-21 (p=0.001) and IL-23 (p=0.001) were significantly elevated." (PMID 30123395, 2018). "IL-21 and IL-23 were significantly elevated in patients with renal failure than in mild disease." (PMID 32264832, 2020). "Patients who developed renal failure had significantly elevated levels of IL-21 (p=0.006) and IL-23 (p=0.002), while those having liver involvement had significantly elevated levels of IL-21 (p=0.001), IL-23 (p=0.001), and TNF-α (p=0.008) compared to the healthy controls." (PMID 30123395, 2018).
respiratory infection (2 papers, 2022 to 2023). "Here, we use the murine model of C. muridarum respiratory infection and IL-21R deficient mice to further identify a novel role of IL-21/IL-21R in neutrophilic inflammation." (PMID 35693111, 2022). "In summary, our research highlights the critical role of IL-21/IL-21R signaling in promoting macrophage polarization towards M1 phenotypes and the pro-inflammatory effects of M1 during C. muridarum respiratory infection." (PMID 37628738, 2023). "Our results found the pathological effects of IL-21/IL-21R in C. muridarum respiratory infection through inducing excessive neutrophil infiltration, with IL-21R deficient mice exhibited less chemokines and proinflammatory cytokines responses." (PMID 35693111, 2022). "It is emphasized that the IL-21/IL-21R signaling may play a role in recruiting mononuclear macrophages from the peripheral blood to infected sites during C. muridarum respiratory infection." (PMID 37628738, 2023). "Our results revealed that IL-21/IL-21R could promote the infiltration of pulmonary Mφ and induce polarization towards M1-type pro-inflammatory Mφ during C. muridarum respiratory infection." (PMID 37628738, 2023). "Therefore, it is particularly important to study whether IL-21/IL-21R aggravates chlamydia respiratory infection by regulating Mφ." (PMID 37628738, 2023). "However, the latent mechanism and effects of IL-21/IL-21R on innate immune response in C. muridarum respiratory infection remain unclear, thus warranting further investigation." (PMID 35693111, 2022). "In this study, combined with the suggestions from the bioinformatic analysis, we used the animal models of C. muridarum respiratory infection of IL-21R−/− mice and the RAW264.7 macrophage cell lines to clarify the role of IL-21/IL-21R on Mφ in vivo and in vitro." (PMID 37628738, 2023).
Salmonella Infections (2 papers, 2016 to 2018). Infections with bacteria of the genus SALMONELLA. "It has been reported that IL-17 and its associated cytokines (IL-21 and IL-22) are induced in the gastrointestinal tract during Salmonella infection." (PMID 27891321, 2016). "After Salmonella infection, the amount of IL-4 and IL-21 was strongly upregulated in CD4+ T cells of MyD88−/−, but not MyD88+/+, mice." (PMID 29973931, 2018).
tendinopathy (2 papers, 2014 to 2019). "This project aimed to investigate the role and expression of the cytokine/receptor pair IL-21/IL-21R in human tendinopathy." (PMID 24757284, 2014). "Secondly it may be that IL-21 expression occurs extremely early in the “tendinopathy spectrum” and that our cohort represents a later stage in the pathological process; however, we feel that the alternative ligand binding theory of IL-21R is a more likely scenario within tendinopathy pathology." (PMID 24757284, 2014). "Despite a lack of IL-21 expression, these data again suggest that early tendinopathy has an inflammatory/cytokine phenotype, which may provide novel translational targets in the treatment of tendinopathy." (PMID 24757284, 2014).
viral myocarditis (2 papers, 2020 to 2023). Myocarditis that is caused by an infection with a viral agent. "Some results have suggested that As IV can reduce IL-4, IL-5, and IL-17 levels to inhibit asthmatic effects and improve cardiac functions in children with viral myocarditis by reducing the levels of IL-17, IL-21, and caspase-3." (PMID 32317974, 2020).
visceral leishmaniasis (2 papers, 2017 to 2019). A severe form of leishmaniasis characterized by irregular bouts of fever, substantial weight loss, swelling of the spleen and liver, and anemia (which may be serious). "IL-21 transcripts are detectable following cutaneous leishmaniasis caused by Leishmania panamensis, Leishmania major, and Leishmania braziliensis infections as well as in humans and mice infected with Leishmania donovani, the causative agent of visceral leishmaniasis." (PMID 31867283, 2019). "In a study of human visceral leishmaniasis, pro-inflammatory cytokines acting on splenic macrophages had the potential to upregulate IL-27, which in turn induced IL-21 to expand IL-10+CD4+CD25−Foxp3− T cells as a mechanism of positive feedback control." (PMID 29033934, 2017). "CD3+ T cells were the major source of IL-21 expression during visceral leishmaniasis in humans." (PMID 31867283, 2019).
acute leukemia (1 paper, 2013). A clonal (malignant) hematopoietic disorder with an acute onset, affecting the bone marrow and the peripheral blood. "The IL-17 and IL-21 serum concentrations showed statistically significant higher levels in acute leukemia patients compared to healthy volunteers (P < 0.0001 for IL-17 and IL-21, respectively, for both ALL and AML)." (PMID 24085544, 2013). "Using ELISA, we found that serum levels of IL-17 and IL-21 in untreated acute leukemia patients were significantly higher than in controls and correlated positively with levels of circulating Th17 cells." (PMID 24085544, 2013). "In this study, we determined the prevalence of circulating Th17 cells and serum concentration of their related cytokines IL-17 and IL-21 in adult acute leukemia patients to evaluate their potential impact on disease outcome." (PMID 24085544, 2013). "Demonstration of the effect of IL-21 in acute leukemia cell lines and acute leukemia patients remains unproven." (PMID 24085544, 2013). "Serum levels of IL-17 and IL-21 were significantly elevated in acute leukemia patients." (PMID 24085544, 2013).
alopecia (1 paper, 2025). Hair loss usually from the scalp. "Our results indicated that as the severity of alopecia increased from mild to severe, there was a corresponding increase in the levels of IL-6, TNF-α, IL-17A, and IL-21." (PMID 41002719, 2025).
anterior uveitis (1 paper, 2013). Inflammation of the iris and anterior chamber of the eye. "For this reason, further studies are needed in order to confirm the possible IL2/IL21 genetic region influence on the non-anterior uveitis genetic background." (PMID 23676143, 2013). "Our results indicate that analyzed IL2/IL21, IL2RA and IL2RB polymorphisms do not seem to play a significant role on the non-anterior uveitis genetic predisposition although further studies are needed in order to clear up the influence of these loci on the non-anterior uveitis susceptibility." (PMID 23676143, 2013).
autoimmune peripheral neuropathy (1 paper, 2024). "Thus, the development of autoimmune peripheral neuropathy in NOD.AireGW/ mice was associated with IL-21 upregulation in peripheral nerve CD4+ T cells." (PMID 39087473, 2024). "Together, these findings demonstrate a critical role for IL-21 in disease pathogenesis and reveal multiple new molecular targets for the treatment of autoimmune peripheral neuropathies." (PMID 39087473, 2024). "IL-21–expressing CD4+ T cells, as crucial pathogenic immune cell types, characterize mouse models of autoimmune peripheral neuropathies similar to chronic inflammatory demyelinating polyneuropathy and Guillain-Barré syndrome." (PMID 39087473, 2024). "IL-21 signaling is essential for the development of autoimmune peripheral neuropathy." (PMID 39087473, 2024).
autoimmune type 1 diabetes (1 paper, 2024). Autoimmune disease wherein the body's own immune system attacks and destroys the cells within the pancreas that produce insulin. "In an IL-21R-deficient non-obese diabetic (NOD) mouse model for autoimmune (type 1) diabetes, IL21 signaling was demonstrated to be indispensable for disease onset." (PMID 38720888, 2024).
B-cell neoplasm (1 paper, 2015). A group of heterogeneous lymphoid tumors generally expressing one or more B-cell antigens or representing malignant transformations of B-lymphocytes. "Altogether, these data indicate that IL21 induces an imbalance in the expression of pro- and anti-apoptotic genes in CLL cells and suggest that IL21-mediated pro-apoptotic mechanisms are common to different B-cell neoplasms." (PMID 26305332, 2015).
babesiosis (1 paper, 2019). Babesiosis refers to a condition caused by microscopic parasites that infect the red blood cells. "The evidence supporting potential protective roles of the IL-21/IL-21R signaling axis during experimental murine babesiosis is limited." (PMID 31867283, 2019). "Collectively, the lack of experimental evidence demonstrating a direct and protective role played by the IL-21/IL-21R signaling axis precludes a definite conclusion as to how this signaling axis regulates host immunity during experimental babesiosis and may warrant further future studies." (PMID 31867283, 2019).
benign breast tumours (1 paper, 2025). "An important discovery of our research is the statistically significant negative correlation between IL-21 and IL-22 concentrations in the blood serum of women with benign breast tumours." (PMID 40729006, 2025).
benign prostatic hyperplasia (1 paper, 2011). A non-cancerous nodular enlargement of the prostate gland. "We evaluated local IL-2, IL-7, IL-15 and IL-21 gene expression in prostate tissues from patients with early stage PCA or benign prostatic hyperplasia (BPH)." (PMID 21943235, 2011).
Bladder Cancer (1 paper, 2019). "MB49 bladder cancer cells were transfected with expression plasmid pT7TS encoding mouse GM-CSF and human IL-21, and then irradiated with 100 Gy at 4 days later." (PMID 31467912, 2019). "In the present study, we have shown that vaccination with tumor cells coexpressing GM-CSF and IL-21 elicited potent antitumor responses in a mouse model of bladder cancer." (PMID 31467912, 2019). "A vaccine of irradiated bladder cancer cells coexpressing GM-CSF and IL-21 was compared with vaccines expressing either factor on its own for the ability to prevent growth of mouse bladder cancer tumors." (PMID 31467912, 2019). "Irradiated bladder cancer cells overexpressing both GM-CSF and IL-21 are more effective than cells expressing either factor alone as a vaccine against bladder cancer." (PMID 31467912, 2019). "In summary, our results suggest that coexpression of GM-CSF and IL-21 in a whole-cell cancer vaccine can enhance efficacy against bladder cancer in mice." (PMID 31467912, 2019).
cervical cancer (1 paper, 2014). A primary or metastatic malignant neoplasm involving the cervix. "Also, we observed the elevated levels of TGF-β, IL-6, IL-17 and IL-21 in cervical cancers (unpublished observations)." (PMID 24523865, 2014).
childhood asthma (1 paper, 2024). "Our analysis focused on four proteins, IL‐21, MICB, PDE4D, and RGAP1, which exhibited effects in both MR analyses involving risk factors and childhood asthma outcomes." (PMID 38730525, 2024). "Elevated levels of seven proteins (TLR4, UBP25, CBR1, Rac GTPase‐activating protein 1 [RGAP1], IL‐21, MICB, and PDE4D) and decreased levels of three proteins (GSTO1, LIRB4 and PIGF) were associated with an increased risk of childhood asthma." (PMID 38730525, 2024). "Hence, the specific mechanisms by which MICB, PDE4D, and IL‐21 proteins affect the onset of childhood asthma will require further experimental evidence for elucidation." (PMID 38730525, 2024). "Based on the genetic data of 4419 (of 4489) plasma proteins from UK Biobank, our study presents compelling evidence linking 10 plasma proteins (GSTO1, LIRB4, PIGF, IL‐21, MICB, PDE4D, RGAP1, TLR4, UBP25 and CBR1) to childhood asthma." (PMID 38730525, 2024).
chlamydial infection (1 paper, 2023). "In order to test the participation of interleukin-21 and its receptor (IL-21/IL-21R) in macrophages (Mφ) against chlamydial infection, we quantified IL-21R expression on the pulmonary Mφ by flow cytometry." (PMID 37628738, 2023). "Interleukin-21 and its receptors (IL-21/IL-21R) aggravate chlamydial lung infection, while macrophages (Mφ) are one of the main cells infected by chlamydia and the main source of inflammatory cytokines." (PMID 37628738, 2023). "IL-21/IL-21R signaling is involved in regulating diseases caused by various pathogens, not just chlamydia, and chlamydial respiratory infection is not solely associated with this signal." (PMID 37628738, 2023).